CTLA4 (cytotoxic T-lymphocyte associated protein 4)
Diseases named in the same sentence as CTLA4 in open-access papers (continued):
Sharing a sentence is not in itself a finding about the gene and the disease.
autoimmune disease (continued). "Cytotoxic T-lymphocyte-associated protein 4 (CTLA-4) and programmed cell death protein-1 (PD-1) are proteins that regulate the activity of T cells and play a role in preventing autoimmune diseases." (PMID 39684895, 2024). "It is believed to play an important role as an immunosuppressive factor in cancer immunity, infection immunity, autoimmune diseases, and immune checkpoint molecules, such as PD-1 and CTLA-4." (PMID 38668032, 2024). "Risk factors for irAEs’ recurrence after ICI retreatment include an immunological background (i.e., autoimmune disease history or autoantibodies’ positivity), anti-CTLA-4 regimen, and younger age." (PMID 39796705, 2024). "Genes related to these autoimmune diseases and Th17 cell differentiation, including CTLA4, IFN-ALPHA-8, IL12RB2, TRAV3, TRAV16, FOS, and VEGFA, were up-regulated in the E. coli group but down-regulated in the BL + E." (PMID 39707535, 2024). "For autoimmune diseases, there is only one checkpoint stimulator, abatacept, a CTLA4-Ig fusion protein, one of the therapeutic options for rheumatoid arthritis." (PMID 38279272, 2024). "As targeting specific molecules on the surface of autoreactive B and T cells, such as CD19, BCMA, CD20, and CTLA-4, cellular therapies are emerging as promising approaches for the treatment of autoimmune diseases." (PMID 39676874, 2024). "From another perspective, CTLA-4 knockout mice experience severe autoimmune diseases and eventually die due to excessive lymphocyte proliferation within 3–5 weeks." (PMID 39290500, 2024). "Due to the inhibitory function of CTLA-4, targeting CTLA-4 has shown promise as a therapeutic approach in animal models of autoimmune diseases and transplant rejection." (PMID 39290500, 2024). "The exact function of CTLA-4 in lupus development and activity is unclear; however, genetic, serological, and mouse studies provide evidence for its role in autoimmune diseases." (PMID 38399467, 2024). "The antibody-mediated blocking of CTLA-4 prevents the development of tolerance, enhances the anti-tumor response, and exacerbates autoimmune disease." (PMID 38807592, 2024). "This makes CTLA4 an immunotherapy target for various autoimmune diseases and cancers, and blocking the CTLA4 pathway contributes to enhancing the immune response and attacking cancer cells." (PMID 38226966, 2024). "The expression of CTLA-4 in activated T cells and Treg cells has been reported to play a crucial role in the regulation of the therapeutic efficacy of ICIs in autoimmune diseases and cancer." (PMID 39795946, 2024). "After integrating the data of SLE, RA, and GO, it was found that rs11571315, rs733618, rs4553808, rs16840252, and rs11571319 of CTLA4 and rs36084323 of PDCD1 had a significant statistical association in these three autoimmune diseases." (PMID 37760867, 2023). "Therefore, reduced Treg function may explain autoimmune diseases in CTLA-4 deficiency." (PMID 36756122, 2023). "Further study highlighted that CD8+ T cells can modulate various cytokines, including CTLA-4, and play a role in the pathogenesis of autoimmune diseases such as SLE, MS, and T1D." (PMID 37497212, 2023). "The soluble form of CTLA-4, capable of binding CD80, is implicated in the pathogenesis of several autoimmune diseases, in which sCTLA-4 is able to inhibit early T-cell activation by blocking the interaction between CD80 and the costimulatory receptor CD28." (PMID 37483633, 2023). "More and more data have suggested that CTLA-4 is crucial in the onset and progression of autoimmune diseases, and this is confirmed by the effects of CTLA-4Ig in the treatment of autoimmune diseases." (PMID 37497212, 2023). "It is reasonable to believe that through the study of the CTLA-4 immune regulation signaling pathways and effects on various autoimmune diseases, there will be benefits for the treatment of autoimmune diseases." (PMID 37497212, 2023).
autoimmune disease (continued). "These factors are collectively referred to as immune-checkpoint molecules, which include CTLA-4 and PD-1/PD-L1, and their implication in autoimmune diseases." (PMID 38137632, 2023). "Our analysis was able to confirm the role of anti‐CTLA‐4 CPI as a predictor for the development of irAEs and supports the finding of poor kidney function (a parameter included in CCI) and autoimmune disease as additional risk factors." (PMID 37084178, 2023). "The decrease in CTLA-4 expression on the cell surface and its functional stability is believed to increase T-cell activation, which can lead to the development of autoimmune diseases." (PMID 37128592, 2023). "Elucidating the immunoregulatory mechanisms and roles of CTLA-4 in autoimmune diseases will provide potent immunotherapy targets for these diseases." (PMID 37497212, 2023). "Several single nucleotide polymorphisms (SNPs) have been identified within this gene, and some of them have been related with the ability of CTLA-4 to inhibit immune responses, playing an important role in the development of autoimmune diseases or cancer." (PMID 37122695, 2023). "Risk factors for developing irAEs are the administration of high doses of ICI (only while using CTLA-4 inhibitors), preexisting autoimmune diseases and obesity (through the proinflammatory metabolic state)." (PMID 36204105, 2022). "Knocking out PD1 in animal models results in the development of lupus-like systemic autoimmune diseases, On the other hand, knocking out CTLA-4 in animals, leads to more fatal autoimmune diseases as compared to PD-1 knockouts." (PMID 36213163, 2022). "The first promising results of exploiting the inhibitory activity of CTLA-4 in animal models of autoimmune diseases were presented over 25 years ago." (PMID 35634292, 2022). "Abatacept with the CTLA4-Ig fusion protein shows efficacy in the treatment of autoimmune disorders, including RA." (PMID 35955790, 2022). "Earlier it has been identified that ICOS, CTLA4 and CCR6 polymorphism is related to autoimmune disease risk in patients with Sarcoidosis28–30." (PMID 35075176, 2022). "The association between the CTLA4 +49 G/A and CT60 gene variants and the development of different autoimmune diseases have been previously suggested." (PMID 36163113, 2022). "Murine Treg-specific CTLA-4 depletion leads to the spontaneous development of systemic lymphoproliferation and T-cell-mediated autoimmune diseases, and an impaired suppressive function." (PMID 36059538, 2022). "Hypophysitis is a novel autoimmune disease specific for immune checkpoint inhibitor therapies, especially of the anti-CTLA-4 one." (PMID 36213163, 2022). "Engaging this pathway with CTLA-4:Ig it has been shown to be an effective treatment, highlighting that this pathway plays a role in maintaining immune reaction during autoimmune disease." (PMID 35784333, 2022). "These two CTLA-4-Ig molecules have been investigated in multiple autoimmune disorders, including RA, T1DM, diffuse cutaneous systemic sclerosis (dcSSc), psoriasis, and SLE." (PMID 35784333, 2022). "As the CD226–TIGIT axis is centrally involved in the Th1/Th17 balance in cancer and autoimmunity, possible side effects of TIGIT blockade include exacerbation of autoimmune diseases similar to combined PD-1/CTLA-4 blockade." (PMID 35410311, 2022). "Forms of these autoimmune diseases are similar to anti-CTLA-4 therapy, except arthritis and pneumonitis." (PMID 36213163, 2022). "An increase in Treg FOXP3 and CTLA4 expression would stabilise the Treg cell phenotype and benefit patients with autoimmune disease." (PMID 34408239, 2021). "Many established autoimmune-disease drug targets, such as TNF blockers, IL23/IL12 antagonists, and CTLA4 agonists, have either prospectively or retrospectively been shown to reside in GWAS loci of autoimmune diseases." (PMID 33798443, 2021).
autoimmune disease (continued). "Immune homeostasis acts to prevent autoimmune disease, and the CTLA-4 and PD-1 pathways are vital for this balance, but also involved in anticancer immune response exhaustion and suppression." (PMID 34790123, 2021). "Although elimination of CTLA-4 can result in several diseases including autoimmune diseases, effective anti-tumor immunity sometimes requires the blockade of CTLA-4." (PMID 34497832, 2021). "The CTLA-4–Ig fusion protein, abatacept, has shown promise in treating rheumatoid arthritis in humans, while its use in various autoimmune diseases is being tested in clinical trials." (PMID 33717075, 2021). "The PTPN22, CTLA4, and BACH2 loci are well-known drivers of autoimmune disease and we identified the variants and haplotype blocks that have previously been described in AAD and common autoimmune comorbidities." (PMID 33574239, 2021). "Recently, checkpoint inhibitors PD-1 and CTLA-4 have been used as therapeutic targets for immune disorders, tumors, autoimmune diseases and neuroinflammatory diseases such as Alzheimer’s disease." (PMID 34025669, 2021). "Since treatment of cancer patients with checkpoint-inhibitors (anti-CTLA4) has led to autoimmune diseases as serious adverse events, we next treated healthy female WT mice with CTLA4-AB, starting at age 11 weeks." (PMID 32089545, 2021). "PDCD1, like CTLA4, plays a negative regulatory role in T-cell activation to develop immune tolerance, which can prevent the development of autoimmune diseases or prevent the immune system from killing cancer cells." (PMID 34671352, 2021). "Clinical CTLA4 haploinsufficiency often results in a CVIDid phenotype with hypogammaglobulinemia and autoimmune disease, and functional Treg dysfunction has been described." (PMID 34247288, 2021). "Factors that predict irAEs, such as history of autoimmune disease, use of CTLA-4 inhibitors, and poor kidney function of grade 3 or higher, have been investigated and reported to date." (PMID 33673446, 2021). "The overactivation of the T/B cell was regulated by CTLA-4 and CD40 gene variants which has been confirmed in the pathogenesis of autoimmune diseases including GD." (PMID 33568133, 2021). "Cytotoxic T-lymphocyte antigen-4 (CTLA-4) and Programmed death-ligand 1 (PD-L1), as inhibitory immune checkpoints, participate in terminating the development of numerous autoimmune diseases, including MS." (PMID 34442365, 2021). "Correspondingly, anti-CTLA4 treatment of cancer patients can result in autoimmune disease as serious adverse event." (PMID 32089545, 2021). "Polymorphic variants of CTLA-4 gene are implicated in dysregulation of immune homeostasis due to an aberrant activation of T-lymphocytes in the periphery which may cause the infiltration of glands leading to their dysfunction and autoimmune disease development." (PMID 32974248, 2020). "This makes particular sense in light of the remarkable, yet limited utility of anti-CTLA-4 antibodies in the treatment of cancers and of CTLA-4-Ig in autoimmune disorders like rheumatoid arthritis." (PMID 33384695, 2020). "CTLA4-Ig (Abatacept) has been produced to suppress immune response by inhibition of T cells functions in autoimmune disease." (PMID 33680034, 2020). "Exacerbation of autoimmune disease symptoms has been more frequently observed in patients receiving PD-1 or PD-L1 inhibitors than CTLA-4 inhibitors (62% vs. 36%)." (PMID 33330040, 2020). "The ability of CTLA4 to inhibit T cells and limit the immune response has raised this molecule as a target for treating autoimmune diseases." (PMID 33680034, 2020). "A gene locus in chromosome 2q33, which contains CTLA4 and CD28, is associated with the risk of T1DM, autoimmune thyroiditis and other autoimmune diseases." (PMID 33272321, 2020). "Abatacept, a Soluble fusion protein consists of the extracellular domain of CTLA4 and FC fragment of IgG molecule, was generated to prevent some autoimmune diseases especially Rheumatoid Arthritis." (PMID 33680034, 2020).
autoimmune disease (continued). "Previous researches have confirmed that biologics targeting immune checkpoints, such as abatacept, which targets the CTLA-4 related immune checkpoint, have high potential for clinical application in treating autoimmune diseases." (PMID 32793241, 2020). "Here we demonstrated the contribution of polymorphic variants of genes encoding IL2RA, CTLA-4, and IFIH1 to autoimmune diseases predisposition." (PMID 32974248, 2020). "We analyzed a cohort of 305 ME/CFS patients and 201 healthy controls for potential disease association of the PTPN22, CTLA4, TNF, and IRF5 SNPs that were described to be risk loci for various autoimmune diseases." (PMID 32328064, 2020). "CTLA-4 has a significant therapeutic effect on transplant rejection and various autoimmune diseases." (PMID 31223621, 2019). "Mice specifically lacking the inhibitory receptor CTLA-4 in Treg cells succumb to fatal autoimmune disease, indicating that CTLA-4 plays a major role in suppressive function." (PMID 30856173, 2019). "Our data suggest that the interaction surface between RGMB and sCTLA-4 presents a novel therapeutic target for both autoimmune diseases and tumors, especially in cases where systemic alteration of CTLA-4 induces adverse effects." (PMID 31061392, 2019). "A Cytoscape network diagram in our study showed that PD-L2 in PDAC is closely related to the expression of PD-L1, CD86, TNFRSF14, PD-1, CD160 and CTLA-4, which are important for the regulation of immunodeficiency and autoimmune diseases." (PMID 31464648, 2019). "On the contrary, autoimmune disease would develop by reducing CTLA4 transcription level because of the immune responses are overreacting." (PMID 31684013, 2019). "The CTLA-4 gene is located on chromosome 2 (2q33) and it has been shown that CTLA-4 is associated with various autoimmune diseases such as T1DM, Graves’ disease and asthma." (PMID 31771625, 2019). "By targeting the CD80 and CD86 molecules through CTLA-4 chimera proteins, both abatacept and belatacept became the earliest approved treatments against various autoimmune diseases, including rheumatic arthritis and juvenile idiopathic arthritis." (PMID 31597242, 2019). "Cytotoxic T lymphocyte-associated protein 4 (CTLA-4), programmed cell death 1 (PD-1), and PD-1 ligand (PD-L1) are coinhibitory molecules that can restrain the immune response to prevent autoimmune diseases." (PMID 31293523, 2019). "The critical nature of CTLA-4’s influence on co-stimulation for the maintenance of immune homeostasis is demonstrated by the numerous autoimmune disorders that develop upon its abrogation in both mice and humans." (PMID 31061392, 2019). "Four genes CTLA4, IL2RA, ICOS, and IL7R have been associated with a group of autoimmune diseases in GWAS and with autoimmunity in the HPO database." (PMID 31695696, 2019). "Although co-stimulation by CD28 on T cells is essential for modulating the T-cell immune response in autoimmune diseases, inhibitory pathways by CTLA-4 on T cells are also critical." (PMID 31747403, 2019). "The major role of PD-1, in contrast to the CTLA-4, is to restrict the T-cell activation in peripheral tissues, to prevent from autoimmune disease and to maintain tolerance within the TME." (PMID 31340499, 2019). "Cytotoxic T lymphocyte antigen-4 (CTLA-4) expressed only on activated T cells is an immunoregulatory molecule and plays a role in the pathogenesis of autoimmune disorders." (PMID 29850619, 2018). "CD28 is non-redundant for Tregs, as CD28-deficient mice have reduced Treg numbers and develop exacerbated autoimmune diseases, suggests a potential deleterious effect of CTLA4-Ig." (PMID 29973932, 2018). "CTLA-4 is expressed predominantly in Treg cells where it suppresses autoimmune diseases by downregulating B7-1 and B7-2 expression on DCs26 among other potential mechanisms." (PMID 29472691, 2018).
autoimmune disease (continued). "Since genetic inactivation of CTLA-4 expression leads to autoimmune diseases in mouse and human, it is assumed that the irAE would be a necessary price to pay for CITE." (PMID 29463898, 2018). "In contrast to the function of CD80/CD86, CTLA-4 can transmit an inhibitory signal to T cells to avoid some autoimmune diseases in normal people." (PMID 32793247, 2018). "A similar fatal autoimmune disease occurs if CTLA-4 is deleted from Tregs using Cre/lox with the FoxP3 promoter, due to loss of Treg suppressive function, particularly, lack of Treg-mediated DC CD80 and CD86 expression." (PMID 29706961, 2018). "Genetic studies in autoimmune disease identified polymorphisms in IL-2 pathway genes encoding IL-2RA (CD25), IL-2, CTLA-4 and PTPN2 as key drivers in autoimmune disease susceptibility." (PMID 30446251, 2018). "Except for HLA, CTLA-4 and CD40 are apparently the most popular susceptibility genes in autoimmune diseases." (PMID 30223781, 2018). "The deficiency of the CTLA-4 gene produces serious autoimmune disorders similar to those induced by defective FOXP3, demonstrating that CTLA-4 is essential for Treg function." (PMID 28589115, 2017). "In the case of CTLA-4, studies have shown that autoimmune disease in Ctla4−/− (i.e. CTLA-4) mice depend on CD28 expression." (PMID 31544130, 2017). "Previous studies on soluble CTLA-4 show increased plasma concentrations in several autoimmune disorders, but low or undetectable levels in healthy individuals." (PMID 28056053, 2017). "Blockade of CTLA-4 results in autoimmune disease and colitis in normal mice, exacerbates diabetes in diabetes-prone non-obese mice, and abrogates Treg cell-mediated suppression." (PMID 28555139, 2017). "The expression of CTLA-4 on T cells depends on cell activation induced by the CD28–B7 interaction, and systemic inflammatory diseases, such as infectious or autoimmune diseases, induce high expression of CTLA-4." (PMID 26901565, 2016). "Considering the beneficial role CTLA-4 was suggested to play in down-regulation of autoimmune diseases including CD, this result deserves further examination." (PMID 27367722, 2016). "Previously we have attempted to deliver cytoplasmic domain of CTLA-4 protein which inhibits T cell receptor signaling pathway in activated T cells modulated abnormal immune responses in allergic or autoimmune disease models." (PMID 27186978, 2016). "The administration of decoy co-inhibitory receptors, such as CTLA-4.Ig or agonistic antibodies, can suppress the response of self-reactive T cells in autoimmune diseases." (PMID 27965674, 2016). "The 3’ UTR of CTLA4 gene has also been found to be involved in several autoimmune diseases hence to study the genetic variation of such regions is imperative." (PMID 26963610, 2016). "Accumulating evidence indicates that co-inhibitory molecules, such as CTLA-4, PD1, and BTLA, are negative regulators of immune responses since deficiencies or mutations result in the development of autoimmune diseases." (PMID 27965674, 2016). "Although anecdotal, these descriptions raise the question of the current exclusion of anti-CTLA-4 treatment in patients with autoimmune disease, given the poor prognosis of a metastatic cancer." (PMID 26337719, 2015). "Given the importance of CTLA-4-mediated suppression in the control of autoimmune diseases, our novel data highlight the importance of vitamin D in inflammatory settings." (PMID 26134669, 2015). "A soluble form of CTLA-4 (sCTLA-4) has been detected at high concentrations in several autoimmune diseases, and its possible functional meaning has been suggested." (PMID 25383768, 2014). "CTLA4’s strong binding affinity to B7 led to the design of protein-based therapeutics, linking the CTLA4 extracellular domain to an antidody Fc domain (CTLA4-Fc), that is already approved for use in autoimmune diseases and transplantation." (PMID 25227919, 2014).